MMP9 (matrix metallopeptidase 9)
Diseases named in the same sentence as MMP9 in open-access papers (continued):
Sharing a sentence is not in itself a finding about the gene and the disease.
lung carcinoma (continued). "Besides, miR-182-5p upregulated the expression of Twist, MMP-2 (matrix metallopeptidase 2), MMP-9 (matrix metallopeptidase 9), N-cadherin, Vimentin, and Snail proteins, which promoted the EMT process in lung cancer." (PMID 34729113, 2021). "There are reports that BAP31 knockdown reduces expression level of TGF-β1, MMP-2, MMP-9, ROCK1, α-SMA, Vimentin and N-cadherin in cervical cancer, and BAP31 affects F-actin distribution to promote migration and invasion of lung cancer cells." (PMID 34179078, 2021). "Treatment of A549 and H1299 cells with the PI3K inhibitor, AKT inhibitor, or NFκB inhibitor led to decreased levels of both MMP2 and MMP9 in the media, suggesting the likely involvement of these proteins in the mechanism regulating the levels of MMP2/9 in the media of these lung cancer cells." (PMID 34209215, 2021). "Moreover, miR-106b enhanced the expression of MMP-2 and MMP-9 and targeted PTEN to promote lung cancer cell migration and invasion." (PMID 34281588, 2021). "Western blot analyses revealed that the protein expression of AKT1, IL6, VEGFA, MMP9 in lung tissue of COPD and lung cancer was significantly increased in the model group and hesperetin could dose-dependently prevent these protein expressions (P < 0.01)." (PMID 34262419, 2021). "MiR-210 in lung cancer cell-derived EVs is transferred to fibroblasts, where it inhibits TET expression, leading to CAF differentiation, activation of JAK/STAT signaling, and expression of pro-angiogenic VEGF, MMP9, and FGF2." (PMID 32957712, 2020). "Previous studies have shown that IOP can change energy metabolism through the LKB1/AMPK pathway and induce lung cancer cell apoptosis; IOP can also reduce the expression of MMP-2 and MMP-9 by downregulating the NF-κB signaling pathway, thereby inhibiting the migration and invasion of B16-F10 cells." (PMID 33282634, 2020). "Inhibition of MMP‐9‐mediated lung cancer migration and invasion via honokiol was evaluated in the present study, and the migration and invasion activity of H1299 lung cancer cells was suppressed under the noncytotoxic concentration of honokiol treatments." (PMID 32180962, 2020). "Depletion of ABL1 and ABL2 protein kinases in PC9-AA and HCC827-AA lung cancer cells impaired the increase of MMP9 but not MMP2 gelatinase activity induced by MSCs." (PMID 33119681, 2020). "Thus, suppression of migration and invasion is triggered by promoting HDAC6-mediated HSP90/MMP-2 or MMP-9 dissociation and followed by MMP-2 and MMP-9 degradation in breast and lung cancer cells." (PMID 32961679, 2020). "Notably, we found that ABL tyrosine kinases are activated in MSC-primed lung cancer cells and functional ABL kinases are required for MSC-induced MMP9 expression, secretion and proteolytic activity." (PMID 33119681, 2020). "Similarly, MMP9 secretion was markedly enhanced in HCC4006 and H1650 lung cancer cells co-cultured with MSCs." (PMID 33119681, 2020). "Nonetheless, MMP9 expression regulation by the KRAS/IKKβ pathway in these cells is likely unimportant, as targeting either KRAS or IKKβ in both lung cancer cell lines did not affect MMP9 enzymatic activity." (PMID 32823550, 2020). "Nano-EGCG may inhibit lung cancer cell invasion through matrix metalloproteinase (MMP)-2- and MMP-9-independent mechanisms." (PMID 32198390, 2020). "Together, the interactions between lung cancer cells and macrophages through ERα/CCL2/CCR2/MMP9 and CXCL12/CXCR4 pathways could promote the NSCLC progression." (PMID 32356397, 2020). "Furthermore, the analysis of the correlation of tumor stage and MMP‐9 expressions reveals that high expression of MMP‐9 is found more in stage III and IV of lung cancer than stage I and II (El‐Badrawy, Yousef, Shaalan, & Elsamanoudy, 2014)." (PMID 32180962, 2020).
lung carcinoma (continued). "Moreover, through Western blot analysis of lung cancer cells treated with lung CSC‐derived exosomes, we demonstrated that expression levels of N‐cadherin, vimentin, MMP‐9 and MMP‐1 were up‐regulated, whereas E‐cadherin expression was down‐regulated." (PMID 32396269, 2020). "Similar results were observed upon co-culture of HCC827 lung cancer cells with MSCs resulting in enhanced MMP9 but not MMP2 gelatinase activity." (PMID 33119681, 2020). "In conclusion, results of the present study provide experimental evidence that myricetin can inhibit invasion and migration of radioresistant lung cancer cells (A549‐IR) by suppressing the expression of MMP‐2 and MMP‐9 through inhibition of the FAK‐ERK signaling pathway." (PMID 32328272, 2020). "In the present study, honokiol, an active compound from Magnolia officinalis plant, suppressed lung cancer cell migration and invasion via the inhibition of MMP‐9 activity, rather than MMP‐2." (PMID 32180962, 2020). "In addition, curcumin has been found to reduce MMP-9 protein level in A549 cells by downregulating PKCα, NOX-2, and ATF2 expression, and inhibiting ROS intracellular production in lung cancer A549 cells." (PMID 31817718, 2019). "Among these, MMP-9 and MMP-2 play a critical role in the progression of lung cancer." (PMID 29565268, 2018). "For example, MMP9 enhances CD44 cleavage and shedding, and CD44-mediated cell migration in glioblastoma xenograft cells, while CD44 regulates hyaluronan-dependent MMP2 secretion and tumor invasiveness in human lung carcinoma cells." (PMID 30002682, 2018). "Recently, it was found that casticin could inhibit the invasion of lung cancer stem-like cells through down-regulation of Akt phosphorylation (p-Akt) and matrix metalloproteinase (MMP) 9 (MMP-9) activity." (PMID 30401729, 2018). "On the basis of their lung-tumorigenesis promoting functions, the MMP members MMP-1, MMP-2, MMP-7, MMP-9 and MMP-10 may result promising biomarkers for lung cancer." (PMID 29207990, 2017). "In addition, acacetin suppressed TPA-induced cell invasion and MMP-9/uPA activities, and the suppression of JNK1/2 pathway in human lung cancer cells." (PMID 29267213, 2017). "In this study, we found that curcumin stimulates the expression of miR-98, which in turn negatively regulates LIN28A-induced lung cancer invasion and migration may through inhibition MMP2 and MMP9." (PMID 28587210, 2017). "Statistically significant higher serum levels were confirmed for MMP-7 (P = 0.014) and MMP-9 (P < 0.001) when comparing lung cancer with non-cancer patients (both healthy and benign)." (PMID 29207990, 2017). "In the two COPD patients (out of 39), who were incidentally diagnosed with lung cancer metastasis, the levels of these serum biomarkers were determined [VEGF (2658.0, 1013.5 pg/ml), IL-8 (11.8, 23.7 pg/ml), MMP-9 (661.8, 1166.7 ng/ml) and MMP-2 (209.2, 95.7 ng/ml)]." (PMID 27811960, 2016). "Specifically, the enzymatic activity of MMP9, the expression of which strongly correlates with poor prognosis in lung cancer, was not activated by TGFβ treatment in Snail knockdown-TD cells." (PMID 27015122, 2016). "Similar to H3F3A, GPR87 knockdown significantly decreased lung cancer cell invasion (P=1.5 × 10−3, t-test) and MMP9 expression (P=9.5 × 10−3, t-test), but did not affect proliferation ability." (PMID 27694942, 2016). "Our results indicated that basigin-2 could regulate the downstream molecules MMP-2, MMP-9 and VEGF expression and contributed to a promotion in migration, invasion and proliferation of lung cancer cells." (PMID 27042161, 2016).
lung carcinoma (continued). "In our study, we showed that basigin-2 was highly expressed in the lung cancer bone metastases and could regulate the downstream molecules MMP-2, MMP-9 and VEGF expression, which promoted migration, invasion and proliferation of lung cancer cells." (PMID 27042161, 2016). "Then, we demonstrated that basigin-2 could promote lung cancer cells invasion, metastasis and proliferation through upregulating metalloproteinases-2 (MMP-2), MMP-9 and vascular endothelial growth factor (VEGF) expression." (PMID 27042161, 2016). "Three regions: 3p14.2 (deletion), 9p21.2q21.31 (amplification), and 20q13.12 (amplification) were commonly found in HN4 and HN31 as the same cluster in our analysis, and five genes (FHIT, MMP9, GNA14, GNAQ, and PSAT1) were involved in tumorigenesis in lung cancer and colon cancer." (PMID 27501229, 2016). "Our results indicated that basigin-2 could regulate its downstream molecules MMP-2, MMP-9 and VEGF expression and promote migration, invasion and proliferation of lung cancer cells." (PMID 27042161, 2016). "Second, miR-206 can directly regulate mRNA expression by targeting the 3′-UTR of MET and BCL2, and inhibit protein expression of cyclin D1 and gene expression of cyclin D1, cyclin D2 and matrix metalloproteinase 9 (MMP-9), while increased p57 gene expression in lung cancer cell (A549)." (PMID 26325180, 2015). "MMP-9 was induced in ERK dependent signaling to promote invasion in colorectal cancer, and TIMP2 was noted as a transcriptional signature in inhibiting tumorigenesis and metastasis of lung cancer cells." (PMID 25033461, 2014). "The data presented in this study suggest that DLK1 can promote the invasion of lung cancer cells by upregulating MMP9 expression, which depends on Notch signaling." (PMID 24621612, 2014). "We also blocked MMP-2 and MMP-9 functions with MMP-2 and MMP-9 neutralizing antibodies, respectively, and found that astrocyte CM containing neutralizing antibodies reduced its ability to induce both breast and lung cancer cell invasion." (PMID 24324647, 2013). "MMP-2 and MMP-9 plays a crucial role in tumor invasion and angiogenesis by mediating degradation of the extracellular matrix, and inhibition of MMP activity has been shown to suppress lung cancer metastasis." (PMID 22662257, 2012). "As demonstrated in this study, CypA upregulated the activity of MMP9 in NSCLC cells, which could help elucidate the mechanism of CypA effect on lung cancer metastasis." (PMID 23031673, 2012). "Overexpression of MMPs, in particular gelatinase A (MMP-2), gelatinase B (MMP-9) and stromelysin-3 (MMP-11), is related to tumour progression and metastasis in solid tumours including gastric, colon and lung cancer." (PMID 12771921, 2003). "Another investigation found that FA could hinder the proliferation of H1299 cells, cell viability, and proliferation assay in vitro at a concentration of 0.06–0.6 μM of TFA in lung cancer by upregulating ROS, hydrogen peroxide, and superoxide anion and downregulating MMP2 and MMP9." (PMID 40487371, 2025). "Given the important role of SP in promoting inflammation and tumor progression, along with the critical involvement of MMP-9 and MMP-2 in cancer metastasis, we hypothesize that SP may promote lung cancer progression and metastasis through pathways involving MMP activity." (PMID 40321254, 2025). "In addition, in lung cancer cells, LCL161 drugs could up-regulate the expression of MMP9 protein and thus induce cancer cell migration." (PMID 39759114, 2025). "Additionally, Chemerin can upregulate pro-angiogenic factors such as VEGF-A, MMP-9, MMP-2, and S100A9 in neutrophils through the activation of the MEK/ERK signaling pathway, thereby facilitating tumor vascularization and bone metastasis in lung cancer." (PMID 38571500, 2024).
lung carcinoma (continued). "We observed significant differences in the MMP-2 and MMP-9 concentrations between the -735CC and -735CT genotypes, as well as the -1562CC and -1562CT genotypes, respectively, not only among the lung cancer subtypes but also among the healthy non-smokers and smokers." (PMID 37445754, 2023). "Moreover, the MnPB NPs could inhibit lung cancer metastasis through downregulating the matrix metalloproteinase (MMP)-2 and MMP-9 expression in A549 cells." (PMID 35814022, 2022). "We found two combinations that can distinguish lung cancer patients with stage IIB from those with IIA with 100% sensitivity and 100% specificity, wherein IL-6, glucose, and LDH has an AUC = 0.8333 and the combination of CEA, IL-6, SAA1, MMP-9, and lactate an AUC = 1.0000." (PMID 34439874, 2021). "Notably, nano-EGCG could suppress the invasion activity of lung cancer through MMP-2- and MMP-9-independent mechanisms; this differs from how EGCG was reported to exert effects on lung adenocarcinoma cells." (PMID 32198390, 2020). "The inhibitory effect of ABL kinase inhibition on MMP9 secretion is selective because loss of ABL function did not impair secretion of other MMPs or the EGFR ligand amphiregulin (AREG), which is induced by MSC-priming in lung cancer cells." (PMID 33119681, 2020). "However, our results demonstrated that nano-EGCG might inhibit lung cancer cell invasion through an MMP-2- and MMP-9-independent pathway." (PMID 32198390, 2020). "Accordingly, the results designated that the stimulation of MMP‐9 protein instability and degradation via honokiol was triggered by inhibiting the function of HDAC6‐mediated Hsp90 chaperone and followed by the suppression of lung cancer cell migration and invasion." (PMID 32180962, 2020). "Importantly, G-Rh2 had a preference to decrease the expression levels of VEGF, MMP2, and MMP9 in co-cultured lung cancer cells, over than those in lung cancer cells without co-culturing." (PMID 29783929, 2018). "To further verify the role of NDUFA4 in the growth and metastasis of lung cancer cells, we detected the expression of cell-growth-related molecules including CDK2, CDK3, CDK4, and CDK6, as well as metastasis-related molecules including CXCR4, E-Cadherin, MMP2, MMP3, and MMP9, respectively." (PMID 28325285, 2017). "Our study showed that NMI suppressed tumor growth by inhibiting PI3K/AKT, MMP2/MMP9, COX-2/PGE2 signaling pathways and p300-mediated NF-κB acetylation, and predicted a favorable prognosis in human lung adenocarcinomas, suggesting that NMI was a potential tumor suppressor in lung cancer." (PMID 29025423, 2017). "Numerous reports in the literature have evaluated the utility of combined tumor-related markers for lung cancer detection and, consequently, we tested whether MMP-1, MMP-7 and MMP-9 could provide complementary discrimination and improve the performance of MMP-9." (PMID 29207990, 2017). "Additionally, the inhibition of MMP-3 or MMP-9 could achieve similar results in NCI-H446 and A549 cells, confirming the crucial role of MMPs in TNF-α promoting lung cancer cell migration." (PMID 27556690, 2016). "However, we didn’t find significant difference between the levels of serum MMP-9 in metastatic and non-metastatic lung cancer patients." (PMID 27811960, 2016). "In lung cancer, JWH-015 and Win55,212-2 inhibit in vitro chemotaxis, chemoinvasion and in vivo tumor growth and lung metastasis via inhibition of AKT, matrix metalloproteinase 9 expression (MMP-9), but the pretreatment of CB1/CB2 selective antagonists, AM251 and AM630 antagonized their effects." (PMID 25115386, 2014).
lung carcinoma (continued). "Since the upregulation effects of Au-NPs on MMP-9 and ICAM-1 expression in A549 and 95D cell suggested that small particles might possess the ability to facilitate the invasion of lung cancer cells, further in vivo studies are required to confirm the mechanisms." (PMID 24901215, 2014). "Moreover, the MMP-1, MMP-2, MMP-9, and MMP-10 were found in the media of the ex vivo 3D lung model as well as in the serum of the blood samples collected from the superior vena cava and pulmonary veins of the lobectomy lung cancer specimens." (PMID 23028922, 2012). "Moreover, there is a study that found that circDENND4C was also highly expressed in lung cancer, but it was not known whether circDENND4C boosted MMP-9 expression to modulate malignant behaviors of NSCLC cells." (PMID 40034591, 2025). "The results showed that the expression of MMP9 and MMP12 in lung cancer tissues was higher than that in normal tissues adjacent to cancer, and the expression of CD36 and FABP4 in lung cancer tissues was lower than that in normal tissues adjacent to cancer." (PMID 37978381, 2023). "Considering the functional characteristics of CDC20, CDC45, TRIM37 and MMP9, it is not surprising that BARX1 promotes cellular proliferation, migration and invasion of lung cancer cells by transactivating CDC20, CDC45, TRIM37 and MMP-9 expression." (PMID 37587140, 2023). "Similar regulatory patterns were observed in the expression of MMP9 and MMP2 mRNA by G-Rh2 in two lung cancer cell lines with or without being co-cultured." (PMID 29783929, 2018). "Econazole also specifically decreased the expression levels of Bcl-2 but not MMP-9 or VEGF, suggesting that econazole induces apoptosis in lung cancer cells." (PMID 29269744, 2017). "Several studies have reported that plasma and/or serum levels of MMP-9 and TIMP-1 are elevated in stage III/IV lung cancer patients, when compared with patients with nonmalignant lung diseases." (PMID 27375834, 2016). "In another lung cancer cell line A549, the anti-metastatic effect of CTD remained different as it only inhibited the gelatinous efficacy of MMP-2, but not MMP-9, while the expression level of either MMP-2 or MMP-9 had not changed." (PMID 32707651, 2020). "Notably, the effect of ABL kinase inhibition on MMP9 secretion appears to be selective as secretion of amphiregulin (AREG), which is markedly enhanced by co-culture of MSCs with lung cancer cells, was not decreased by treatment with either GNF5 or ABL001." (PMID 33119681, 2020). "MMPs, such as MMP-3, MMP-9, MMP-13 were negative prognostic factors for lung cancer survival." (PMID 27556690, 2016). "Expression of MMP9 was greatly increased in PC9 scrambled control (SCR) cells co-cultured with MSCs versus PC9 cells grown in the absence of MSCs, and knockdown of ABL kinases in PC9 (AA) lung cancer cells markedly decreased the MSC-mediated induction of MMP9 mRNA expression." (PMID 33119681, 2020).